SLFN11 (schlafen family member 11)
Diseases named in the same sentence as SLFN11 in open-access papers (continued):
Sharing a sentence is not in itself a finding about the gene and the disease.
melanoma (4 papers, 2019 to 2024). A malignant, usually aggressive tumor composed of atypical, neoplastic melanocytes. "For instance, type I IFNs induced the expression of SLFN5, SLFN11, SLFN12, and SLFN13 in normal melanocytes, but in melanoma cell lines, only SLFN5 was inducible." (PMID 38791884, 2024). "Although SLFN11, SLFN12, SLFN13, and SLFN14 are expressed comparably in primary melanocytes and malignant melanoma cells, the high expression of SLFN5 in primary melanocytes is suppressed at both mRNA and protein levels in malignant melanoma cells." (PMID 34571887, 2021). "The role of SLFN11 in IFNγ mediated toxicity seems to be context-dependent because SLFN11 was shown to be required for IFNγ mediated toxicity in HAP1 cells but not in prostate or melanoma cell lines." (PMID 38791884, 2024).
triple-negative breast carcinoma (4 papers, 2021 to 2025). An invasive breast carcinoma which is negative for expression of estrogen receptor (ER), progesterone receptor (PR), and human epidermal growth factor receptor 2 (HER2). "Higher levels of SLFN11 have been linked to increased sensitivity to DNA-damaging chemotherapies, including PARP inhibitors, leading to improved PFS and OS in triple-negative breast cancer." (PMID 40224185, 2025). "Recent research from our group has found knock-out of SLFN11 in a prostate cell line did not cause resistance to olaparib nor did low SLFN11 levels in triple-negative breast cancer (TNBC)-rich cohort of PDX models." (PMID 34663950, 2021). "Moreover, RB1 loss (in combination with impaired BRCA-mutant signature and high SLFN11 expression) was highly predictive for the response of patient-derived xenografts of triple-negative breast cancer to irinotecan (SN-38 is the active metabolite of irinotecan)." (PMID 33591981, 2021).
Fanconi anemia (3 papers, 2021 to 2026). Fanconi anemia (FA) is a hereditary DNA repair disorder characterized by progressive pancytopenia with bone marrow failure, variable congenital malformations and predisposition to develop hematological or solid tumors. "We further identify the USP1-WDR48 deubiquitinase complex as a positive modulator of SLFN11 activation in PrimPol-deficient cells, revealing an addiction to the Fanconi anaemia pathway to resolve cisplatin lesions." (PMID 41514018, 2026). "We confirmed this role of SLFN11 in cells with the genome instability disorder Fanconi anemia (FA), in which the compromised fork stability is ameliorated by the depletion of SLFN11, but also in the wild-type setting." (PMID 37833372, 2023).
glioblastoma (3 papers, 2021 to 2025). The most malignant astrocytic tumor (WHO grade IV). "In glioblastoma, target the interaction between SLFN11 and the NF - κB pathway and verify whether it can reverse the characteristics of tumor stem cells." (PMID 40766331, 2025). "In glioblastoma (GBM), the SLFN11 gene is highly expressed, and it promotes GBM progression by negatively regulating the non-classical NFκB signaling pathway." (PMID 40766331, 2025). "In glioblastoma multiforme (GBM), high levels of all human Schlafens (SLFN5, SLFN11, SLFN12, and SLFN13) are correlated with shorter overall survival of patients." (PMID 34571887, 2021).
lung adenocarcinoma (3 papers, 2017 to 2020). A carcinoma that arises from the lung and is characterized by the presence of malignant glandular epithelial cells. "Furthermore, cisplatin treatment of lung adenocarcinoma cell lines with high endogenous levels of SLFN11 showed a subsequent reduction in expression (A549, P=0.002; H1944, P<0.0001; HCC827, P=0.001), but not those with low levels (Calu6, P=0.785)." (PMID 28212573, 2017). "The strong positive Spearman's correlation for lung squamous carcinoma contrasted with a lack of correlation for lung adenocarcinoma (r = −0.01, p = 0.89), further suggesting that the relationship between CD47 and SLFN11 expression is cancer type specific." (PMID 31632920, 2019).
acute lymphoblastic leukemia (2 papers, 2021 to 2025). Leukemia with an acute onset, characterized by the presence of lymphoblasts in the bone marrow and the peripheral blood. "For example, SLFN11 expression is elevated in acute myeloid leukemia (AML) and acute lymphoblastic leukemia (ALL) cells." (PMID 40766331, 2025).
bladder cancer (2 papers, 2025). "A study on the prognostic role of SLFN11 in bladder cancer only evaluated the expression score of SLFN11 in tumor cells and found that SLFN11 was associated with better overall survival (OS) in patients receiving platinum - based chemotherapy (p = 0.012)." (PMID 40766331, 2025). "In patients with gastric and bladder cancer, high SLFN‐11 expression is a predictor of efficacy of platinum‐based chemotherapy." (PMID 39809728, 2025). "SLFN11 is a predictive biomarker for bladder cancer patients receiving platinum-based chemotherapy, and its expression level can specifically predict chemotherapy response and patient survival outcomes." (PMID 40766331, 2025).
Chronic myelogenous leukemia (2 papers, 2019 to 2020). "Conversely, the selective HDAC6 inhibitor Rocilinostat, which did not induce SLFN11 in K562 chronic myelogenous leukemia or HT1080 fibrosarcoma cells, was 1.51-fold less potent for CD47− vs. WT cells in the CellTiter Glo assay and was less potent for inhibiting proliferation of CD47− cells." (PMID 31632920, 2019).
clear cell renal cell carcinoma (2 papers, 2022 to 2025). "SLFN11 is a key tumor promoter and poor prognostic marker for clear cell renal cell carcinoma (ccRCC)." (PMID 40766331, 2025). "Overexpression of SLFN11 is an independent prognostic factor for clear cell renal cell carcinoma." (PMID 40766331, 2025). "It has been reported that SLFN11, a cellular restriction factor, is closely related to tumor immune lymphocytes, immune checkpoint genes, chemokines, and immune-related signaling pathways in clear cell renal cell carcinoma, which is similar to our bioinformatics analysis." (PMID 36211333, 2022).
Colon cancer (2 papers, 2018 to 2021). "Conversely, expression of cyclin D1 and cyclin E1 increases after knockdown of SLFN11 in DKO colon cancer cells that express high endogenous SLFN11." (PMID 34571887, 2021). "Moreover, methylation of SLFN11 (which correlates with SLFN11 expression) significantly correlates with age, poor 5-year overall survival, and poor 5-year relapse-free survival in colon cancer." (PMID 34571887, 2021). "Knockdown of SLFN11 increases chemoresistance of cancer cells to a broad range of DNA damaging agents, and ectopic expression of SLFN11 sensitizes colon cancer cells to topoisomerase I inhibitors, consistent with the involvement of SLFN11 in the DNA damage response." (PMID 29423044, 2018). "Therefore, SLFN11 methylation (which inversely correlates with SLFN11 expression) could serve as an independent prognostic factor for overall and relapse-free survival in colon cancer." (PMID 34571887, 2021). "Colon cancer tissues show consistently negative immunohistochemical labeling for SLFN11." (PMID 34571887, 2021). "Hypermethylation of the SLFN11 CpG promoter inactivates SLFN11 gene expression in cancer cells, which might contribute to the reported negative SLFN11 labeling in colon cancer." (PMID 34571887, 2021).
esophageal squamous cell carcinoma (2 papers, 2020 to 2021). Esophageal squamous cell carcinoma (ESCC) is a type of esophageal carcinoma (EC) that can affect any part of the esophagus, but is usually located in the upper or middle third. "High SLFN11 expression is correlated with a better prognosis in esophageal squamous cell carcinoma patients." (PMID 34571887, 2021). "Therefore, SLFN11 expression could be a prognostic marker for esophageal squamous cell carcinoma and a potential biomarker for therapy selection in esophageal squamous cell carcinoma." (PMID 34571887, 2021). "In this study, we examined the prognostic value of SLFN11 expression in esophageal squamous cell carcinoma (ESCC) patients treated with definitive chemoradiotherapy (dCRT), including the platinum derivative nedaplatin." (PMID 33218331, 2020).
gastric adenocarcinoma (2 papers, 2022 to 2024). "All these data supported our findings in gastric adenocarcinoma cells that inhibiting ABCG2 activity in cancers with high SLFN11 expression can increase the efficacy of SN-38." (PMID 39033209, 2024). "The findings revealed that SLFN5, SLFN11, SLFN12, SLFN12L, SLFN13, and SLFN14 were expressed at higher levels in many cancers, including GC (stomach adenocarcinoma; STAD), while the SLFN14 expression levels were relatively low in all tumor and normal tissues." (PMID 36090985, 2022).
head and neck squamous cell carcinoma (2 papers, 2022 to 2025). A squamous cell carcinoma that arises from any of the following anatomic sites: lip and oral cavity, nasal cavity, paranasal sinuses, pharynx, larynx, and salivary glands. "In this study, we examined whether SLFN11 expression was associated with the therapeutic outcome of platinum-based CRT in head and neck squamous cell carcinoma (HNSCC)." (PMID 36741698, 2022). "Patients with head and neck squamous cell carcinoma (HNSCC) have significant differences in their responses to cisplatin-based chemoradiotherapy (CRT), and SLFN11 expression levels have been revealed as a key prognostic factor that can predict treatment benefit." (PMID 40766331, 2025).
liver cancer (2 papers, 2020 to 2024). An epithelial or non-epithelial malignant neoplasm that arises from the liver. "The article suggests that CCL2-dependent macrophage infiltration and M2-like polarization, along with the upregulation of PD-L1 in tumor cells, represent the potential mechanisms by which SLFN11 deficiency facilitates immune evasion in liver cancer." (PMID 39558948, 2024).
lymphoma (2 papers, 2021 to 2025). A malignant (clonal) proliferation of B- lymphocytes or T- lymphocytes which involves the lymph nodes, bone marrow and/or extranodal sites. "The EZH2 and HDAC epigenetic modifiers upregulated SLFN11 expression in GCB-derived lymphoma cells and made them more susceptible to cytosine arabinoside." (PMID 33513156, 2021). "Based on these results, we conclude that SLFN11 expression is suppressed epigenetically by histone post-translational modifications concomitantly with ABC-DLBCL-associated genes in GCB-derived lymphomas." (PMID 33513156, 2021). "Moreover, we show that epigenetic activation of SLFN11 in lymphomas of GCB origin enhances their susceptibility to the clinical DNA-damaging agent cytosine arabinoside, which targets DNA replication." (PMID 33513156, 2021). "Treatment with epigenetic modifiers such as the HDAC inhibitor, Panobinostat, significantly upregulated SLFN11 expression across various GCB-derived lymphoma cell lines, indicating that histone acetylation can reverse the suppression of SLFN11." (PMID 41303540, 2025). "We tested the effects of two epigenetic modifiers, an EZH2 inhibitor, tazemetostat (EPZ6438) and a histone deacetylase inhibitor, panobinostat (LBH589) on SLFN11 expression in GCB-derived lymphoma cell lines." (PMID 33513156, 2021). "GCB-derived lymphomas with low SLFN11 expression can be treated by the combination of epigenetic modifiers and cytosine arabinoside." (PMID 33513156, 2021). "Our data consolidate these findings with GCB-derived lymphoma cell lines and provide a rationale to treat B-cell lymphoma with low SLFN11 expression by combining tazemetostat with AraC." (PMID 33513156, 2021). "SLFN11 overexpression further sensitized GCB-derived lymphoma cells to cytosine arabinoside." (PMID 33513156, 2021). "We find that SLFN11 is typically suppressed in GCBs (centroblasts and centrocytes) and GCB-derived lymphomas." (PMID 33513156, 2021). "The expression of SLFN11 is epigenetically suppressed in normal GCBs and GCB-derived lymphomas." (PMID 33513156, 2021).
mesothelioma (2 papers, 2021 to 2025). A usually malignant and aggressive neoplasm of the mesothelium which is often associated with exposure to asbestos. "As for the combination therapy of PARPi and TMZ, SLFN11 expression appears to mainly correlate with sensitivity to PARPi treatment, however, in mesothelioma cell lines and SCLC in vivo models SLFN11 expression also correlated with increased response to PARPi and TMZ combination treatment." (PMID 34085099, 2021). "Similarly, in mesothelioma cells, high SLFN11 expression correlated with response to PARP inhibitors, and combination with temozolomide enhanced the sensitivity of cells with low MGMT expression, further supporting the broad potential of SLFN11 as a biomarker of DNA damage response." (PMID 40766331, 2025).
metastatic cancer (2 papers, 2021). A carcinoma which has spread from the original site of growth to another anatomic site. "Interestingly, SLFN11 was significantly elevated in metastatic cancer (P = 0.04, Wilcoxon test), when compared to the primary cancer group." (PMID 33339894, 2021).
metastatic tumor (2 papers, 2021 to 2022). "GR-CDXL4 samples also strongly expressed SLFN11 with 70%, 90%, and 90% cell positivity in the CDX, the CDX-derived cell line, and the mouse metastatic tumor, respectively." (PMID 35511434, 2022). "Another study examined the patient-derived xenografts (PDXs) response to DDA and has shown SLFN11 is significantly elevated in metastatic tumors compared to non-metastatic ones, and high SLFN11 metastatic PDXs showed better response to therapy with DNA damaging agents." (PMID 34571887, 2021).
osteosarcoma (2 papers, 2023). A usually aggressive malignant bone-forming mesenchymal neoplasm, predominantly affecting adolescents and young adults. "We first transiently expressed human SLFN11 tagged with GFP at its C-terminus in the osteosarcoma cell line U2OS, which does not express SLFN11, treated with the sensitizer Hoechst33342, and applied 405 nm laser irradiation." (PMID 37833372, 2023).
prostate adenocarcinoma (2 papers, 2019 to 2021). "Analysis of tumor data in TCGA also implicated CD47 regulation of SLFN11 promoter methylation in a subset of cancers that includes prostate adenocarcinoma." (PMID 31632920, 2019). "In contrast, SLFN11 is not overexpressed in neuroendocrine prostate cancer patients treated with platinum, and it has remained lower than CRPC with adenocarcinoma histology, indicating that SLFN11 upregulation in response to platinum-based chemotherapy is specific to prostatic adenocarcinoma." (PMID 34571887, 2021).
prostate tumor (2 papers, 2019 to 2021). "For a broad collection of cancer cell lines, SLFN11 mRNA in prostate tumors was negatively correlated with methylation of the SLFN11 promoter (p = 4.5 × 10−31)." (PMID 31632920, 2019). "SLFN11 mRNA was confirmed to be expressed in his liver metastasis by RNA sequencing and not expressed in his primary prostate tumor." (PMID 34385567, 2021).
adenovirus infection (1 paper, 2019). "Persistent adenovirus infection of B-lymphocytes has been shown to significantly down-regulate several cellular genes (BBS9, BNIP3, BTG3, CXADR, SLFN11, and SPARCL -), however, none are reported to obviously function in the regulation of metabolism." (PMID 31864392, 2019).
ampullary cancer (1 paper, 2025). "We also report low SLFN11 expression in patient 35 with ampullary cancer, a histology in which there is little known about the role of SLFN11 and drug response." (PMID 40439882, 2025).
bladder tumor (1 paper, 2024). "Consistent with its function as a DNA/RNA helicase, in bladder tumor specimens, SLFN11 expression was nuclear and increased expression associated with better clinical outcome following NAC or adjuvant chemotherapy." (PMID 39337385, 2024).
colon adenocarcinoma (1 paper, 2015). "Colon adenocarcinoma samples can have a range of SLFN11 expression to >600 % of the smallest level." (PMID 26525741, 2015).
colorectal tumors (1 paper, 2025). "Higher rates of elevated SLFN11 expression have been reported in SCLC (76%) compared to other tumor histologies represented by our study population (e.g., 5% of colorectal tumors)." (PMID 40439882, 2025).
diffuse large B-cell lymphoma (1 paper, 2021). "SLFN11 mRNA level was found low in both normal GCBs and GCB-DLBCL (GCB like-diffuse large B-cell lymphoma)." (PMID 33513156, 2021).
fibrosarcoma (1 paper, 2020). A malignant mesenchymal fibroblastic neoplasm affecting the soft tissue and bone. "Next, we used a doxycycline-inducible system to express SLFN11 in a fibrosarcoma cell line, HT1080, that does not normally express SLFN11." (PMID 33256675, 2020).
folate deficiency (1 paper, 2019). A nutritional condition produced by a deficiency of FOLIC ACID in the diet. "Thirdly, genes with an opposite expression pattern in folate deficiency and repletion cell lines: SORBS2, DCN, SLFN11, RUNX3, GALC, and HSPB7." (PMID 30836646, 2019).
follicular thyroid cancer (1 paper, 2021). "SLFN11 was higher in the rarer more aggressive follicular thyroid cancer (n = 5) compared to papillary subtype (n = 5) (P = 0.032)." (PMID 34663950, 2021).
genitourinary cancers (1 paper, 2021). "In panels of miscellaneous upper gastrointestinal- and genitourinary cancers, SLFN11 low cell lines were significantly less responsive to gemcitabine monotherapy, but they could be re-sensitised by cotreatment with ATRi." (PMID 33339894, 2021).
glioma (1 paper, 2022). A benign or malignant brain and spinal cord tumor that arises from glial cells (astrocytes, oligodendrocytes, ependymal cells). "However, our findings necessitate careful assessment of such strategies in GBM because stimulation of SLFN11 expression might trigger some undesired glioma-promoting effects." (PMID 36382088, 2022).
HCMV infection (1 paper, 2022). "SLFN11 therefore represents an ARF for HCMV that acts to restrict significantly the spread of HCMV infection." (PMID 35105802, 2022). "Schlafen-11 (SLFN11), an interferon-stimulated gene and restriction factor for retroviruses and certain RNA viruses, potently restricted HCMV infection." (PMID 35105802, 2022). "The intersection between these approaches showed that one particular protein, Schlafen family member 11 (SLFN11), is both down-regulated during the late phase of HCMV infection and is targeted by the RL1-6 block of viral genes." (PMID 35105802, 2022). "SLFN11 potently restricted HCMV infection, inhibiting the formation and spread of viral plaques." (PMID 35105802, 2022). "RL1 might thus prevent SLFN11-mediated repression of ATM/ATR in the presence of the DNA damage response stimulated by HCMV infection in order to benefit viral replication." (PMID 35105802, 2022). "SLFN11 potently restricted HCMV infection and therefore represents a unique HCMV ARF." (PMID 35105802, 2022). "We sought to determine whether SLFN11 restricts HCMV infection." (PMID 35105802, 2022). "During HCMV infection, expression of RL1 was completely inhibited by the addition of PFA, and the profile of RL1 expression inversely correlated with the profile of SLFN11." (PMID 35105802, 2022).
invasive breast carcinoma (1 paper, 2019). A carcinoma that infiltrates the breast parenchyma. "Normal breast tissue similarly lacked the positive correlation between CD47 and SLFN11 observed in invasive breast carcinomas." (PMID 31632920, 2019).
lung squamous cell carcinoma (1 paper, 2021). "SLFN11 expression is prognostically significant and correlates with improved patient outcomes after adjuvant chemotherapy in lung squamous cell carcinoma." (PMID 34571887, 2021). "This indicates a role of SLFN11 in the radiosensitivity of lung squamous cell carcinoma." (PMID 34571887, 2021). "Furthermore, in lung squamous cell carcinoma, but not lung adenocarcinoma, SLFN11 expression correlates with the expression of CD47 (a cell surface molecule that sensitizes cancer cells to radiotherapy and chemotherapy)." (PMID 34571887, 2021).